NLRC4 (NLR family CARD domain containing 4)
Diseases named in the same sentence as NLRC4 in open-access papers (continued):
Sharing a sentence is not in itself a finding about the gene and the disease.
Salmonella Infections (continued). "Noteworthy is also the activation of the NLRC4 inflammasome by active LRRK2 during Salmonella infection." (PMID 33426511, 2021). "Although the roles of NLRP3 and NLRC4 in intestinal immune defense against S. Typhimurium invasion have been studied, their precise functions of spvC-mediated Salmonella infection in the gut remain elusive." (PMID 33384666, 2020). "The phosphorylation of NLRC4, which is activated by PKCδ in Salmonella infection, was necessary in macrophages." (PMID 31707260, 2019). "Of these, actually only NLRC4 inflammasome has been shown to mediate mucosal protection against Salmonella infection." (PMID 29456533, 2018). "For example, in the early stage of Salmonella infection, NLRC4 inflammasome can be activated by Salmonella proteins PrgJ or flagellin." (PMID 29523140, 2018). "NLRC4 has been shown by others to be protective in models of respiratory melioidosis and Salmonella infection." (PMID 28961278, 2017). "NLRC4 has been shown to be protective in models of respiratory melioidosis and Salmonella infection." (PMID 28961278, 2017). "Overexpression of Nlrc4 in human cells lines has shown increased inflammatory response to Salmonella infection." (PMID 26635450, 2015). "Recent studies reported that Nlrc4 phosphorylation by Pkcδ is critical for inflammasome activation induced by Salmonella infection." (PMID 24516390, 2014). "In mice, the NAIP/NLRC4 inflammasome is required to control Salmonella infection." (PMID 40162563, 2025). "Caspase-8 and NLRC4 inflammasomes also play a role in limiting Salmonella infection." (PMID 39513865, 2024). "Furthermore, we found that inhibition of S1PR3 enhanced dsDNA-induced AIM2 inflammasome and salmonella infection-induced NLRC4 inflammasome activation, as indicated by enhanced caspase-1 cleavage." (PMID 36798132, 2023). "Within the first 36 h after Salmonella infection the Naip/NLRC4 inflammasome is required for Caspase-1 mediated cell extrusion associated with IL-18 production whereas at a later time point (>72 h post infection) non-canonical inflammasome activation involving Caspase-11 is needed." (PMID 34497340, 2022). "In murine macrophages, Salmonella infection activates both the NAIP/NLRC4 and NLRP3 inflammasomes." (PMID 35073381, 2022). "In addition, the murine NAIPs and NLRC4 contribute to the inflammasome response during in vivo Salmonella infection." (PMID 35073381, 2022). "Among them, NAIP2 binds to the rod protein T3SS, NAIP1 binds to the needle tube proteins of the T3SS, and NAIP5 and NAIP6 bind to bacterial flagellin and then bind to NLRC4 to promote the activation of caspase-1 and Ser533 in NLRC4 is phosphorylated and activated after Salmonella infection." (PMID 35132346, 2022). "Therefore, the role of NLRP3 and NLRC4 regulated by spvC to drive cell fate decisions between autophagy and pytoptosis in Salmonella infection deserves further investigation." (PMID 34335562, 2021). "In addition, genetic ablation of both NLRC4 and NLRP3 in mice leads to increased susceptibility to Salmonella infection." (PMID 32723297, 2020). "It is widely reported that NLRP3 and NLRC4 inflammasomes are activated during Salmonella infection." (PMID 32723297, 2020). "Although the mechanism of NLRC4 inflammasome inhibition in B cells during Salmonella infection is partially understood, the bacterial effector(s) and mechanism(s) involved in this event and/or the further consequences of YAP phosphorylation are still unknown." (PMID 30103648, 2018). "While the precise nature of this interaction is still a subject of debate, it has been suggested that the NAIP/NLRC4/ASC complex formed after Salmonella infection may recruit NLRP3, potentially amplifying caspase-1 cleavage and subsequent IL-1β cytokine release." (PMID 38124741, 2023). "Subsequent mechanistic studies further revealed that NLRC4 and NLRP3 are physically recruited together into a single macromolecular inflammasome complex during Salmonella infection." (PMID 41062723, 2025).
Salmonella Infections (continued). "Human macrophages undergo NAIP/NLRC4- and NLRP3-dependent inflammasome activation during Salmonella infection, which restricts intracellular Salmonella replication." (PMID 40162563, 2025). "Earlier investigations into inflammasome signaling revealed that NLRC4 and NLRP3 have overlapping and cooperative functions in the host defense against Salmonella infection." (PMID 41062723, 2025). "Salmonella infection can trigger the activation of NLRP3 and NLRC4 inflammasomes which are subsequently involved in pyroptosis and the clearance of bacteria in vivo." (PMID 37155697, 2023). "Recently, both the NAIP/NLRC4 and NLRP3 (NLR pyrin domain-containing protein 3) inflammasomes have been shown to respond to Salmonella infection in human macrophages." (PMID 35073381, 2022). "In mice, in addition to the NAIP/NLRC4 and NLRP3 inflammasomes, Salmonella infection can also activate the caspase-11 inflammasome." (PMID 35073381, 2022). "Our studies uncover a multifaceted inflammasome response to Salmonella infection in human macrophages, and reveal that NAIP/NLRC4 inflammasome-dependent sensing of the SPI-2 T3SS promotes control of intracellular Salmonella." (PMID 35073381, 2022). "NLRC4 and NLRP3 inflammasomes can detect exogenous and endogenous molecules that serve as indicators of Salmonella infection." (PMID 32723297, 2020). "Inflammasomes play a key and multilayered role at distinct stages of immune defense against Salmonella infection, although unexpected redundancy was found among NLRP3 and NLRC4 in vivo." (PMID 32723297, 2020). "Our findings are in lines with previous reports about NLRC4 and NLRP3 co-localization into a unique complex in HEK293 cells and in mice bone marrow-derived macrophages during Salmonella infection." (PMID 31244842, 2019). "In contrast to NLRC4 and NLRP3, NLRP6 and NLRP12 negatively regulate the inflammatory responses during Salmonella infections." (PMID 29594070, 2018). "Previous studies showed that NLRP3 and NLRC4 recruit ASC and caspase-1 in response to bacterial trigger, and both of NLRC4 and NLRP3 are activated during Salmonella infections." (PMID 29594070, 2018). "In that line, Salmonella infection has recently been shown to induce recruitment of both NLRP3 and NLRC4 to the same inflammasome complex along with ASC, caspase-1, and caspase-8." (PMID 28403163, 2017). "Caspase-1, constitutively present in macrophages, requires stimulation of the NLRC4 (NLR family CARD-domain containing protein 4) and NLRP3 (NOD, LRR and pyrin domain-containing 3) receptors for activation during Salmonella infection." (PMID 27808091, 2016). "In mice, intestinal epithelial cells (IECs) are a primary site of Salmonella infection, and epithelial-intrinsic expression of NAIP or NLRC4 is both necessary and sufficient to restrict bacterial burden, indicating a central role for the NAIP/NLRC4 inflammasome in mucosal immunity." (PMID 41304196, 2025). "NLRC4 inflammasome in neutrophils can selective promote the maturation of IL‐1β without the occurrence of pyroptosis during acute Salmonella infection, which is different from the condition in macrophages under the same challenge." (PMID 37817895, 2023). "In mice, the NAIP/NLRC4 inflammasome is important for controlling Salmonella replication in the intestine, whereas the NLRP3 inflammasome is dispensable for control of Salmonella infection in vivo." (PMID 35073381, 2022). "Overall, these data indicate that NAIP and NLRC4 are partially required for inflammasome responses to Salmonella infection in human macrophages, in contrast to what we observe with individual T3SS ligand delivery, where NAIP/NLRC4 is absolutely required for inflammasome activation." (PMID 35073381, 2022).
Salmonella Infections (continued). "Overall, these data indicate that Salmonella infection of human macrophages triggers activation of multiple inflammasomes, and at least two of these inflammasomes, the NAIP/NLRC4, and the NLRP3 inflammasomes, appear to be essential for controlling bacterial replication within macrophages." (PMID 35073381, 2022). "During Salmonella infection, caspase-8 can be recruited to the NLRC4 inflammasome regulating IL-1β secretion, but not playing a role in cell death." (PMID 36532444, 2022). "Because S. Typhimurium induces PANoptosis and previous studies have clearly shown that the NAIP/NLRC4 inflammasome is activated during Salmonella infection, it is highly likely that the NAIP/NLRC4 inflammasome contributes to PANoptosis during bacterial infection." (PMID 33494299, 2021). "On the other hand, type ι interferon-dependent host response performs a negative feedback that represses expression of NLRC4 during Salmonella infection." (PMID 34335562, 2021). "On the other hand, the NLRC4-dependent caspase-1 activation by Salmonella infection was not considerably affected by the knockdown of Drp1 in macrophages." (PMID 26489382, 2015). "Unlike in C57BL/6 mice, in Balb/c mice NLRC4 appears to have a more prominent function in controlling Salmonella infection." (PMID 24381573, 2013). "However, deletion of both NLRC4 and NLRP3 recapitulates the Caspase-1 phenotype completely, confirming a role for both NLRC4 and NLRP3 during Salmonella infection." (PMID 24381573, 2013). "Mice lacking both NLRC4 and NLRP3 are significantly more susceptible to Salmonella infection." (PMID 37155697, 2023). "The results showed that GlcN not only inhibited NLRP3 inflammasome but also reduced IL-1β secretion in AIM2-, non-canonical- and NLRC4-inflammasome activated J774A.1 macrophages, which are stimulated by poly(dA:dT) and LPS transfection or by Salmonella infection, respectively." (PMID 30944389, 2019). "We also found that Ori could not suppress NLRC4 or AIM2 inflammasome activation induced by Salmonella typhimurium (Salmonella) infection or poly A:T transfection, respectively." (PMID 29959312, 2018). "Similar to NLRC4, deficiency in only NLRP3 does not lead to differences in Salmonella infection." (PMID 24381573, 2013). "Moreover, rapamycin-induced autophagy does not inhibit NLRC4 activation stimulated by V. parahaemolyticus or Salmonella infection: thus the mTORC1-PI3K pathway driven by rapamycin might not be involved in interference with the NLRC4 inflammasome." (PMID 23357873, 2013). "Why non-canonical Caspase-11-mediated pyroptosis, like NLRC4-activation accompanied by IL-1β and IL-18 secretion that induces local inflammation and attracts neutrophils, is less potent than Caspase-1-mediated pyroptosis in controlling Salmonella infection remains thus far unclear." (PMID 24381573, 2013). "Indeed, it was shown that NLRC4 could also activate caspase-1 even in the absence of ASC, to induce pyroptosis, ASC however remains to be crucial for cytokine maturation during Salmonella infection." (PMID 25115174, 2014).
melanoma (33 papers, 2012 to 2025). A malignant, usually aggressive tumor composed of atypical, neoplastic melanocytes. "Moreover, loss of NLRC4 or CASP1 promoted melanoma tumor progression." (PMID 34307322, 2021). "A study showed that subcutaneous injection of B16F10 melanoma in Nlrc4-/- mice accelerated tumor growth." (PMID 37020871, 2023). "Recent research confirmed that NLRC4 plays a critical role in inhibiting the progression of melanoma, and lower expression levels of NLRC4 are an adverse factor in inhibiting tumor growth." (PMID 36186792, 2022). "Other studies found enhanced tumor growth in Nlrc4-/- mice after subcutaneous injection of mouse B16F10 melanoma cells, suggesting that NLRC4 is important for regulating signaling pathways responsible for tumor growth control." (PMID 34276697, 2021). "In a murine model of melanoma, NLRC4 was found to suppress tumor growth by non‐inflammasome activation involving interferon‐gamma production from tumor‐associated macrophages." (PMID 32027447, 2020). "In fact, mice injected with B16 melanoma cells or EL4 thymoma cells expressing flagellin from Salmonella typhimurium were shown to display dramatic resistance to tumor establishment in NLRC4 dependent manner." (PMID 25071785, 2014). "In the melanoma Nlrc4-/- mice model, it was identified that NLRC4 inhibits tumor growth." (PMID 40692785, 2025). "NLRC4 was associated with the activation of inflammatory signaling in macrophages and to enhance the production of IFN-γ by CD4+ and CD8+ T cells to inhibit melanoma progression." (PMID 40692785, 2025). "To confirm and extend this finding in human disease, we observed that NLRC4 expression (but not NLRP10 used as control) strongly correlated with expression of the type I IFN genes induced in the NLRC4-expressing cell lines in various patient cancer samples (colon, lung, and melanoma)." (PMID 38652550, 2024). "The role of NLRC4 inflammasomes in melanoma is controversial." (PMID 37020871, 2023). "NLRC4 activation is critical for cytokine and chemokine production in tumor-associated macrophages and is required to generate CD4+ and CD8+ T cells in the B16F10 melanoma mouse model." (PMID 37864090, 2023). "Furthermore, it was reported that Nlrc4-/- mice were shown to have increased tumor development when injected subcutaneously with mouse B16F10 melanoma." (PMID 34327145, 2021). "Therefore, the impairment of NLRC4 inflammasome in melanoma cells and the function in pyroptosis are worth further study." (PMID 34327145, 2021). "NLRC4 is necessary for the generation of IFN-γ–producing CD4+ and CD8+ T cells in the murine model of B16F10 melanoma." (PMID 33494299, 2021). "The fundamental constituent of inflammasomes, comprising pyrin, the NOD-like receptor (NLR) family (NLRP1, NLRP3, NLRP6, NLRP9, and NLRC4), and absent in melanoma 2 (AIM2)." (PMID 39125817, 2024). "Nod-like receptor protein 3(NLRP3), NLR family CARD domain-containing protein 4 (NLRC4), and absent in melanoma 2(AIM2) were indirectly linked to pyrin and other proteins." (PMID 35883480, 2022). "Substantial evidence now exists to support a protective role for NAIP/NLRC4 against the infection with Salmonella typhimurium in vivo, respiratory melioidosis; however, NAIP/NLRC4 inflammasome does not protect against melanoma." (PMID 32630319, 2020). "Accordingly, analysis of anti-PD-1-treated melanoma patients suggested that NLRP6, NLRP7, AIM2, and NLRC4 inflammasomes might contribute to antitumor responses unleashed by checkpoint blockers." (PMID 31085177, 2019). "In contrast, the improved survivals seen with high AIM2 and high NLRC4 were retained in patients with high or low TILs score suggesting the beneficial effect might be intrinsic to melanoma cells and independent of TILs level." (PMID 32027447, 2020).
melanoma (continued). "To explore the broader effects of MLT‐MLP on other inflammasome activation, we established in vitro cell models for the absent in melanoma 2 (AIM2) and NLR family CARD domain‐containing protein 4 (NLRC4) inflammasomes." (PMID 39717013, 2025). "Inflammasomes can be categorized into four subfamilies based on the sensor molecule involved: NLRP3, NLRP1, NLRC4 (NLR family, CARD domain containing 4), and AIM2 (absent in melanoma 2)." (PMID 39226162, 2024). "To date, various inflammasomes, including NLRP1, NLRP2, NLRP3, absent in melanoma (AIM2) and NLRC4, have been identified." (PMID 31941010, 2020). "We found that some inflammasome genes, including CARD domain containing 4 (NLRC4), caspase 5 (CASP5), absent in melanoma 2 (AIM2) and the already mentioned NLRP3, were upregulated in our data." (PMID 30935390, 2019). "S. mutans induced IL-1β secretion via caspase-1 activation, and S. mutans-induced IL-1β secretion required absent in melanoma (AIM2), NLR family pyrin domain-containing 3 (NLRP3) and NLR family CARD domain-containing 4 (NLRC4) inflammasome activation." (PMID 30078841, 2018). "Notably, NLRC4 can promote cytokine and chemokine release in TAMs and amplify protective IFN-γ-producing CD4+ and CD8+ T cells, thereby diminishing tumor growth in melanoma independent of inflammasome assembly." (PMID 35990696, 2022). "Also, riboflavin inhibits the activity of caspase-1, NLRC4 (NLR family CARD domain containing 4), and AIM2 (absent in melanoma), a protein important for several cellular activities, including cell proliferation." (PMID 34959985, 2021). "Also, this includes the following four types; the NLRP3/NALP3 inflammasome, the NLRC4/IPAF inflammasome, the NLRP1/NALP1b inflammasome, and the AIM2 (absent in melanoma 2) containing inflammasome." (PMID 34809705, 2021). "Of note, additional studies have indicated that not only NLRP3, but also NLRP1, NLRC4 [NLR (Nod-like receptor) family CARD-containing 4] and AIM2 (absent in melanoma 2) form the inflammasomes that drive inflammation in response to a wide variety of molecular patterns." (PMID 22701621, 2012). "Moreover, a nucleotide-binding oligomerization domain-like receptor (NLR) protein is the main component of inflammasomes and is classified into four types: NLRP1/NALP1b inflammasome, NLRC4/IPAF inflammasome, NLRP3/NALP3 inflammasome, and AIM2 (absent in melanoma 2) containing inflammasome." (PMID 34067673, 2021). "Indeed, in human, a transcriptomic study has found that the expressions of NLRP1 (NOD-like receptor family pyrin domain containing 1), NLRP3, NLRC4 (NLR Family CARD Domain Containing 4 ) and AIM2 (Absent in Melanoma 2) were reduced in Chinese patients with CRC." (PMID 33255437, 2020).